HIF1A (hypoxia inducible factor 1 subunit alpha)
Diseases named in the same sentence as HIF1A in open-access papers (continued):
Sharing a sentence is not in itself a finding about the gene and the disease.
breast cancer (continued). "Here, we hypothesize that the CXCL12/CXCR4/mTOR/HIF-1α axis in DPP-4-deficient cells plays a key role in the activation of autophagy in breast cancer cells to promote survival." (PMID 37760498, 2023). "Furthermore, the mTOR/HIF-1α axis is associated with breast cancer biology, including epithelial mesenchymal transition (EMT), invasion, metastasis, and resistance to chemotherapy." (PMID 37760498, 2023). "Here, we report that DPP-4 deficiency promotes breast cancer cell survival via the induction of autophagy by the C-X-C motif chemokine 12 (CXCL12)/C-X-C receptor 4 (CXCR4)/mammalian target of rapamycin (mTOR)/hypoxia inducible factor (HIF)-1α axis." (PMID 37760498, 2023). "Knowing that XBP1s has already been reported as a co-activator of HIF-1α in the transcription of the gene encoding GLUT1 (SLC2A1) in breast cancer cells, it was tempting to speculate such a role in our model of proinflammatory macrophages." (PMID 37711626, 2023). "Loss of BRCA1, a mutation of BRCA1, manifested in 45% of hereditary breast cancers was associated with low autophagic activity, leading to an increase in the level of HIF1α and leading to the production of ketone bodies and modulation of the autophagic activity." (PMID 38234683, 2023). "Conversely, BRCA2-mutation-related breast cancers express HIF-1α less frequently." (PMID 36831687, 2023). "From these results, we hypothesized that the higher level of OCN showed that the formation of breast cancer MCs was associated with osteogenic differentiation and that HIF‐1α was involved in the regulation of this process." (PMID 36971046, 2023). "In breast cancer, the level of HIF-1α is closely associated with circRNAs." (PMID 37204526, 2023). "Finally, we found that metformin inhibited the DPP-4 deficiency-stimulated mTOR/HIF-1α/autophagy axis and induced breast cancer apoptosis." (PMID 37760498, 2023). "Furthermore, possibly due to limiting angiogenesis, hypoxia-induced HIF-1α overexpression has been reported to be more than 2-fold more frequent in BRCA1-mutation-associated breast cancer than in sporadic breast cancers." (PMID 36831687, 2023). "Therefore, targeting HIF-1α is expected to overcome therapeutic resistance caused by HIF-1α in breast cancer and improve therapeutic efficacy." (PMID 36003773, 2022). "The association between HIF-1α, stemness, and metabolism was also studied in breast cancer." (PMID 36497394, 2022). "To investigate the role of HIF-1α in breast cancer progression in clinical settings, we analyzed the protein expressions of ATP-HIF-1α signaling-associated genes in 139 breast cancer specimens using tissue microarrays (TMAs), including 40 paired adjacent breast tissues." (PMID 35236823, 2022). "Furthermore, in patients with hereditary breast cancers, positive associations were found between HIF-1α expression and both high tumor grade and shorter relapse-free survival." (PMID 33513753, 2021). "Similarly, in the ER−/TAM− stratum, we observed a near-null association between HIF-1α expression and breast cancer recurrence (OR = 0.97, 95% CI 0.68, 1.39)." (PMID 34736510, 2021). "Moreover, higher levels of both HIF-1α or HIF-2α in breast cancer biopsies are associated with metastasis to regional lymph nodes and distant organs, primary mammary tumor growth, as well as with an increased patient mortality." (PMID 33777815, 2021). "The silencing of Nrf2 has also been linked to impaired HIF-1α activity in breast cancer, suggesting that Nrf2 may regulate HIF-1α expression and/or function." (PMID 31936236, 2020). "The present study aimed to investigate whether hypoxia‐responsive miR‐141–3p was implicated in the pathogenesis of breast cancer via mediating the high‐mobility group box protein 1 (HMGB1)/hypoxia‐inducible factor (HIF)‐1α signaling pathway." (PMID 32436353, 2020). "Knockdown of HIF-1α caused CDCA2 mRNA levels to decline in breast cancer MCF7 cells (GSE3188)." (PMID 32509575, 2020).
breast cancer (continued). "Overall, our work uncovers a ROS/NF‐κB/HIF‐1α axis‐dependent mechanism underlying the anticancer effects of alpinetin and suggests that alpinetin could act as a novel therapeutic agent against breast cancer." (PMID 32562470, 2020). "Moreover, UCA1 has been implicated in hormone therapy resistance in breast cancer cells as it sponges miR-18a, leading to HIF1α activation or inhibition of mTOR signaling, suggesting its multiple functions in breast cancer metabolism." (PMID 33123488, 2020). "SGHZF inhibits breast cancer tumour growth in mice, and the underlying mechanism may be related to the inhibition of Akt and HIF-1α expression." (PMID 33414839, 2020). "In addition to that, the strong association between Nur77 and HIF-1α was also observed in breast cancer specimens." (PMID 33245358, 2020). "HIF‐1α, Kindlin‐2, and Emax could form a new panel of diagnostic markers and therapeutic targets for breast cancer." (PMID 32436609, 2020). "Consistently, overexpression of HIF1α is associated with poor prognosis, treatment resistance and failure, enhanced invasiveness and metastasis, and increased mortality in different types of cancer including breast cancer." (PMID 32092997, 2020). "Our data provide a molecular mechanistic insight indicating that CLDN6 loss may lead to elevated HIF-1α-driven breast cancer metastasis in a SUMOylation-dependent manner." (PMID 32093760, 2020). "Moreover, they showed that increased expression of HIF-1α or HIF target genes in breast cancer biopsies was associated with decreased overall survival." (PMID 30842790, 2019). "Immunohistochemical studies have shown that increased HIF-1α protein levels are linked with increased risk of metastasis in breast cancer patients, suggesting that HIF-1α may serve as a major accelerating factor for cancer cell migration under hypoxia." (PMID 31462898, 2019). "Indeed, hypoxia and increased expression of hypoxia-inducible factor 1α (HIF-1α), the key transcription factor mediating hypoxia response, are associated with endocrine resistance to neoadjuvant and adjuvant therapy in ERα+ breast cancers (7, –9)." (PMID 31152137, 2019). "Previous studies found that HIF-1α was associated with the development and poor prognosis in many cancers, including gastric cancer, breast cancer, and lung cancer, and could change the biological function of a series of genes." (PMID 31582727, 2019). "Importantly, HIF-1α protein expression was associated with tamoxifen resistance in neoadjuvant, primary therapy of ERα-positive breast cancers, as well as resistance to chemoendocrine therapy." (PMID 29342868, 2018). "In addition, ERα mediates estrogenic regulation of HIF-1α in ovarian and breast cancer cells, breast cancer associated fibroblasts and in the rat uterus." (PMID 29996493, 2018). "In addition, loss of HIF-1α in fibroblasts leads to vascular normalization, decreases hypoxia but increases breast cancer development." (PMID 29434587, 2018). "Indeed, our results showed that low Parkin expression is significantly associated with high HIF-1α expression in breast cancer." (PMID 29180628, 2017). "In addition, higher levels of HIF-1α in the diagnostic biopsy of breast cancer patients have been associated with increased metastasis and mortality rate, even in lymph node-negative patients." (PMID 27540529, 2016). "Normoxic HIF1A activation has been linked to anoikis resistance in breast cancer cells." (PMID 27495308, 2016). "HIF-1α expression has been implicated as an independent predictor of a poor outcome for breast cancer patients, suggesting that HIF-1α levels in the diagnostic tumor biopsy could be used to identify patients that are at increased risk of developing metastasis." (PMID 27706047, 2016). "We found that strong HIF-1α expression was associated with increased Axl expression, markers of angiogenesis and other characteristics of aggressive tumors in this cohort of African breast cancer." (PMID 26760782, 2016).
breast cancer (continued). "Moreover, NCOA1 is recruited to the VEGFa promoter by associating with HIF1α and c-Fos in breast cancer cells." (PMID 26287601, 2015). "However, the causal relationship between HIF-1α and endocrine resistance of human breast cancer in vivo remains controversial." (PMID 25929338, 2015). "Therefore, the SNPs located at several proline residues of HIF-1α gene in breast cancer association are potential to modulate the HIF-1α activity." (PMID 25302049, 2014). "Of the 40 studies on the HIF-1α C1772T polymorphism, 6 studies were conducted on prostate cancer, 6 studies on breast cancer, 3 studies on lung cancer, 4 studies on colorectal cancer, 4 studies on renal cancer, 4 studies on oral cancer and 12 studies on other cancers." (PMID 25496056, 2014). "Similarly to P-cadherin, HIF-1α expression is associated to worse prognosis in breast cancer, short patient’s survival, high proliferation and poor tumor differentiation." (PMID 25269858, 2014). "With this data, we could demonstrate that breast carcinomas with positive expression to HIF-1α, GLUT1, CAIX, MCT1 and CD147 are significant associated to tumors showing a high percentage of cancer cells stained for the basal epithelial marker P-cadherin." (PMID 25269858, 2014). "In this study, we found that the significant inhibitions of tumor growth and tumor angiogenesis of breast cancer in female mice by EGCG were associated with suppressing the activation of HIF-1α and NFκB, and decreasing VEGF expression in breast carcinoma cells." (PMID 23638734, 2013). "In conclusion, this study provides strong evidence that YC-1, a potent HIF-1α inhibitor, may be a useful pharmacologic agent which might be used to treat and possibly prevent PR-dependent breast cancer as a result of promoting PR loss." (PMID 23123638, 2013). "Furthermore, functional HIF-1α overexpression (mostly hypoxia induced) is seen at a much higher frequency in BRCA1 mutation-related invasive breast cancer than in sporadic breast cancer." (PMID 23409121, 2013). "Using a refined model system, we investigated whether HIF-1α is directly implicated in the regulation of tumor-initiating cells (TICs) in breast cancer." (PMID 22225988, 2012). "The cause of the control of net mammary tumor growth by HIF-1α is unclear, although our data suggest that HIF-1α-dependent control of TIC activity may be a primary mechanism driving tumorigenesis." (PMID 22225988, 2012). "Mammary tumor epithelial cells were created from MMTV-PyMT mice harboring conditional alleles of Hif1a, followed by transduction ex vivo with either adenovirus β-galactosidase or adenovirus Cre to generate wild-type (WT) and HIF-1α-null (KO) cells, respectively." (PMID 22225988, 2012). "Therefore, if PARK2 is mutated, HIF-1α starts to accumulate and promotes breast cancer metastasis." (PMID 39851497, 2025). "Interestingly, the WWOX/HIF1A ratio appears to be associated with prognosis in patients with various subtypes of breast cancer, brain tumours, and HCC, suggesting it may impact important biological processes in these cancers." (PMID 41007296, 2025). "Hypoxia inducible factor-1α (HIF-1α) which is an oxygen-dependent transcriptional activator that carries out cellular adaptation to low oxygen and nutrient starved environment, is implicated in the ERα mediated activation of the glycolysis process in breast cancer." (PMID 36185256, 2022). "However, whether HIF-1α is the sole critical factor that ATP affects to promote chemoresistance in breast cancer cells and the underlying mechanism involved remain unclear." (PMID 35236823, 2022). "Increased HIF1α expression significantly and inversely correlated with response to Epirubicin therapy and was also shown to be an independent risk factor for resistance to aromatase inhibitor therapy in 187 and 114 oestrogen receptor (ER) positive breast cancer patients, respectively." (PMID 36320041, 2022).
breast cancer (continued). "Thus, there appears to be a positive correlation between Nur77 and HIF-1α expression in breast tumor tissues, which also supports that the mechanism underlying the progression of breast cancer may involve the Nur77/HIF-1α signaling axis." (PMID 33245358, 2020). "In addition, Hif-1α overexpression significantly induced upregulation of various autophagy-related and EMT-associated genes, suggesting that Hif-1α may trigger autophagy and subsequently induce breast cancer metastasis." (PMID 33381039, 2020). "Indeed, HIF-1α expression is associated with survival of breast cancer patients after surgery." (PMID 25089613, 2014). "Therefore, the SNP 1772 C > T of HIF-1α gene is a good predictor for breast cancer risk but may be a poor clinicopathologic-associated factor." (PMID 25302049, 2014). "However, the association of SNP 1772 C > T (rs11549465) of the HIF-1α gene to breast cancer remains unclear in a Taiwanese population." (PMID 25302049, 2014). "The hypoxic microenvironment within breast cancer tumors leads to the sustained activation of hypoxia-inducible factors (HIFs), notably HIF-1α, which, in turn, triggers adaptive responses such as angiogenesis and metabolic reprogramming." (PMID 41614928, 2026). "HIF-1α is an overexpressed isoform in breast cancer, and this characteristic has been clearly identified in precancerous lesions like ductal carcinoma in situ (DCIS) and early-stage breast cancer." (PMID 41614928, 2026). "In vitro, Sulforaphane has been found to reduce the size and number of primary mammospheres in SUM159 and MCF7 breast cancer cells, which are TNBC and ER+, respectively, while downregulating VEGF and HIF-1α in breast cancer cells." (PMID 41614951, 2026). "In both breast cancer cell lines, tramadol treatment significantly extended HIF-1α half-life, supporting the conclusion that it impedes normoxic degradation of the protein." (PMID 41526224, 2026). "Our prior work had demonstrated that tramadol increases HIF-1α protein expression in normoxic breast cancer cells." (PMID 41526224, 2026). "LINC00649 can encourage the growth and spread of breast cancer tumors by maintaining HIF-1α expression." (PMID 41614928, 2026). "Among the phytochemicals discussed, EGCG, resveratrol, and sulforaphane exhibit distinct translational trajectories with respect to HIF-1α inhibition in breast cancer." (PMID 41614951, 2026). "As stated in the previous section, HIF-1α activity in breast cancer dramatically increases under hypoxic settings." (PMID 41614928, 2026). "By reducing HIF-1α buildup, resveratrol has been shown to inhibit proliferation and induce apoptosis, specifically in breast cancer cell lines MCF-7 and MDA-MB-231." (PMID 41614951, 2026). "MiR-155 can inhibit the translation of HIF-1α, lower the activity of the hypoxia signaling pathway, and limit the capacity of breast cancer cells to respond to hypoxia by directly binding to its mRNA." (PMID 41614928, 2026). "The poor prognosis for breast cancer is linked to increased expression of the lncRNAs MIR210HG, which directly binds to the 5′UTR of HIF-1α to stabilize its production." (PMID 41614928, 2026). "Hypoxia can reduce the expression of miR-126, which targets VEGF and HIF-1α to prevent angiogenesis in breast cancer." (PMID 41614928, 2026). "From a translational standpoint, the identification of tramadol as a modulator of the HIF-1α/ATF4 axis provides new insights into therapeutic strategies targeting stress-adaptive pathways in resistant breast cancer subtypes." (PMID 41526224, 2026). "MiR-24 has the ability to specifically control HIF-1α expression in breast cancer stem cells, which enhances the properties of cancer stem cells." (PMID 41614928, 2026).
breast cancer (continued). "In vitro, the resveratrol analogue HS-1793 was shown to inhibit hypoxia-induced HIF-1α expression in breast cancer cell lines (MCF-7 and MDA-MB-23) more than normal resveratrol, acting at a post-transcriptional level." (PMID 41614951, 2026). "But despite the differences in expression, the consistent and definite expression of HIF-1α makes it a valuable target across the studied breast cancer subtypes." (PMID 41614951, 2026). "In vivo, sulforaphane had reduced breast cancer tumor size by 50%, still associated with downregulation of VEGF and HIF-1α in breast cancer, and still using both SUM159 and MCF7 breast cancer cells." (PMID 41614951, 2026). "Through these coordinated responses, HIF-1α promotes tumor cell survival, proliferation, and metastatic dissemination, ultimately contributing to the development of an aggressive breast cancer phenotype." (PMID 41596432, 2026). "At the preclinical level, in vitro, quercetin inhibits hypoxia-related HIF-1α protein accumulation and VEGF release in breast cancer cell lines primarily through inhibition of HIF-1α protein synthesis." (PMID 41614951, 2026). "A novel strategy for overcoming treatment resistance in breast cancer is to target LINC00115 or SETDB1 to modulate HIF-1α signaling." (PMID 41614928, 2026). "LINC00115 functions as a scaffold molecule to control the SETDB1/PLK3/HIF1α signaling pathway in paclitaxel-resistant breast cancer stem cells." (PMID 41614928, 2026). "Although mechanistic and in vivo breast cancer data remain limited, these findings indicate that alkaloids like berberine represent an additional class of phytochemicals capable of modulating HIF-1α–driven hypoxic responses." (PMID 41614951, 2026). "Taken together, our findings indicate that in breast cancer patients, obesity enhances the activation of the FA/HIF‐1α/CCL2 axis in tumor tissues and the CCL2/CCR2/PPARα axis in adjacent adipose tissue." (PMID 41160815, 2026). "Immunofluorescence staining revealed strong nuclear localization of HIF-1α in tramadol-treated breast cancer cells, marked by intensified nuclear red signals in both MDA-MB-231 and MCF-7 cells." (PMID 41526224, 2026). "The lncRNAs SPRY4 intronic transcript (SPRY4-IT1) by controlling the expression of HIF-1α, which is abundantly expressed in breast cancer tissues, can encourage cancer cell metastasis." (PMID 41614928, 2026). "In breast cancer cells, it was reported that HIF-1α gene expression was under the control of estrogen directly through ERα, since this gene contains an estrogen response element." (PMID 40612952, 2025). "In breast cancer cells, berberine and its derivatives arrested the G2/M phase by inhibiting HIF-1α activity and regulating its downstream targets through non-coding RNAs." (PMID 40490812, 2025). "Hypoxia-inducible factor-1α (HIF-1α) has become a significant therapeutic target for breast cancer and other cancers by regulating the expression of downstream genes such as erythropoietin, thereby improving cell survival in hypoxic conditions." (PMID 40421268, 2025). "The present study investigates the role of ZMYND8, a hypoxia-responsive epigenetic factor, in regulating carbohydrate metabolism in concert with HIF1α in breast cancer." (PMID 40912652, 2025). "UBE2S is identified simultaneously with HIF‐1α in human primary hepatic, colon, and breast cancers, metastatic cholangiocarcinoma, and cells of colon cancer." (PMID 41427004, 2025). "In letrozole-resistant breast cancer cells, HIF-1α expression remains constitutively elevated through the HER2–PI3K/Akt/mTOR pathway, driving downstream targets such as BCRP that sustain resistance phenotypes." (PMID 41303593, 2025). "This study highlights the role of ERRα in promoting breast cancer aggressiveness under hypoxic conditions via its interaction with HIF-1α." (PMID 40723264, 2025).